MC4R (melanocortin 4 receptor)
Diseases named in the same sentence as MC4R in open-access papers (continued):
Sharing a sentence is not in itself a finding about the gene and the disease.
Obesity (continued). "For example, loss-of-function variants in MC4R substantially raise obesity risk but can also be present in individuals without obesity." (PMID 40523925, 2025). "Moreover, patients with MC4R deficiency exhibit obesity and respiratory diseases, further insinuating a potential role of MC4R in obesity-related respiratory disorders." (PMID 39542230, 2025). "Understanding these novel mutations in POMC and MC4R/MC3R, as well as their structural and intracellular mechanisms, may help identify strategies for the treatment and diagnosis of obesity, particularly childhood obesity." (PMID 40001512, 2025). "One of the DMRs overlapped with MC4R associated with autosomal dominant and recessive obesity, a phenotype not described in young individual with ARID2-RD." (PMID 40044822, 2025). "In conclusion, results of this study suggest that the MC4R gene might be a candidate gene for obesity in cats." (PMID 40035963, 2025). "While setmelanotide is approved for syndromic obesity, this report highlights a novel anti-inflammatory effect potentially mediated by melanocortin-4 receptor (MC4R) agonism, expanding current understanding of its immunomodulatory role in mast cell–mediated disease." (PMID 41333852, 2025). "MC4R is the most studied MCR, and mutations in its gene are common causes of monogenic obesity." (PMID 40001512, 2025). "The MRAP2 N88Y mutation, identified in one individual with obesity, has not been functionally characterized and our studies indicate it reduces MC4R activity by both the cAMP and IP3 signaling pathways." (PMID 39807633, 2025). "Patients with syndromic obesity (e.g., Bardet‐Biedl syndrome) may also have hyperphagia as a result of neurodevelopmental disruptions in the MC4R pathway." (PMID 40528426, 2025). "Single nucleotide polymorphisms such as FTO rs9939609, MC4R rs17782313, and BDNF rs6265, have been consistently associated with elevated body weight and an increased risk of obesity across diverse populations through their roles in appetite regulation, satiety, and energy balance." (PMID 40423790, 2025). "The emergence of a new therapeutic treatment, the melanocortin-4 receptor agonist setmelanotide (originally RM-493), has represented a breakthrough in the management of monogenic obesity and has raised hope in managing complex obesity." (PMID 39526054, 2024). "Future studies should broaden their scope to include a wider array of genes, such as MC4R, LEP, and POMC, to provide a more comprehensive understanding of the combined association between these genes and breastfeeding and their association with obesity." (PMID 39389470, 2024). "Similarly, the long-term outcomes of bariatric surgery were evaluated in patients with bi-allelic mutations in known monogenic obesity genes such as POMC, LEPR, and MC4R." (PMID 38469147, 2024). "To date, among three out of twenty-two Arab populations, fourteen interactions have been found between the FTO rs9939609, TCF7L2 rs7903146, MC4R rs17782313, and MTHFR rs1801133 polymorphisms and diet or physical activity on obesity and type 2 diabetes outcomes." (PMID 39125399, 2024). "For individuals with a low genetic risk of obesity by FTO, MC4R and BDNF, the effect of water intake on abdominal adiposity may be more pronounced." (PMID 38662725, 2024). "It is unclear whether DNA sequence variation in genes related to obesity, such as the FTO and MC4R genes, affects the outcome of weight loss intervention." (PMID 38674326, 2024). "The trajectory to obesity begs programmatic study of the MC4R KO rat model of obesity." (PMID 39741559, 2024). "To assess whether the anti-obesity properties of GLP-1–MK-801 are dependent on this key energy balance-governing pathway, we tested the weight loss efficacy in DIO Mc4r-KO (also known as melanocortin-4 receptor) mice." (PMID 38750368, 2024). "BBS patients with obesity and/or hyperphagia can be eligible for treatment by MC4R agonists." (PMID 39085583, 2024).
Obesity (continued). "MC4R agonism is a logical therapeutic target for the treatment of obesity." (PMID 38175730, 2024). "In fact, the side effects of hypertension encountered for treatment of obesity with MC4R agonist could also be beneficial in treating refractory septic shock." (PMID 38992428, 2024). "Similarly to MC4R, human genetic variants in MRAP2 have been identified in several families and individuals with obesity and reduce MC4R activity." (PMID 39574659, 2024). "A series of obesity-associated loci identified by genome-wide association studies (GWAS) are confirmed to be related to hypothalamic cilia, including adenylate cyclase 3 (ADCY3) and the melanocortin-4 receptor (MC4R)." (PMID 39126056, 2024). "While MC4R is known to activate Gsα/cAMP signaling, a substantial proportion of obesity-associated MC4R mutations do not affect MC4R/Gsα signaling." (PMID 38175730, 2024). "Genetic exposures included FTO rs9939609, MC4R rs571312, and a pediatric-specific obesity PRS." (PMID 39385774, 2024). "MC3R and MC4R have been investigated as promising targets for anti-obesity drugs." (PMID 38577975, 2024). "Early studies mainly explored obesity-causing genes from a single-gene perspective, and >20 causative genes have been confirmed to be highly associated with the development of obesity, including FTO, PPARG2, LEP, MC4R, and POMC." (PMID 39389470, 2024). "Genetic mutations, like the Melanocortin 4 receptor (MC4R) gene mutation, can lead to obesity." (PMID 39104759, 2024). "Clarifying the divergent MC4R signals that mediate the diverse physiological effects of melanocortins may allow the development of more specific MC4R agonists to treat obesity." (PMID 38175730, 2024). "One study found that the maximum efficacy of β-arrestin recruitment to MC4R, rather than Gαs/cAMP, better explained the variance in the association of MC4R variants with obesity; another study did not." (PMID 37040537, 2023). "The MC4R gene was identified as the leading contributor of monogenic obesity and the interaction of FTO and MC4R genes on certain pathways are associated with obesity-related phenotypes." (PMID 36717394, 2023). "The association of MC4R rs17782313 with an elevated risk of obesity or other related measures is not consistent across different populations, as the causal factors of genetic variants vary across populations." (PMID 38002939, 2023). "Setmelanotide is a potent MC4R agonist which displays both clinical efficacy and minimal undesirable cardiovascular effects and has proven to be a highly promising new addition to the armamentarium for personalised obesity pharmacotherapy." (PMID 37249754, 2023). "Thus, we performed electron microscopic analysis of the livers of MC4R-KO mice fed a Western diet (WD) for 20 wk, which exhibited obesity, insulin resistance, and NASH-like liver phenotypes." (PMID 37725372, 2023). "Hepatocyte-specific ablation of FASN ameliorated NAFLD and diabetes in melanocortin 4 receptor–deficient mice but not in mice with diet-induced obesity." (PMID 37681411, 2023). "MC4R SNPs were associated with the risk of obesity, but there was no significant gene-environment interactions." (PMID 37664850, 2023). "The melanocortin system plays an important role on the regulation of appetite, energy expenditure, and metabolism, therefore, impairments in the POMC and melanocortin 4 receptor (MC4R) pre- and post-translational processing are forerunners for the development of obesity." (PMID 36969815, 2023). "In addition, our ethnically homogeneous study unambiguously shows that the onset of severe obesity is ∼3 years earlier in both LEP and LEPR deficiencies compared with the children deficient for MC4R." (PMID 37659411, 2023). "Several individuals suffer from a deficiency in POMC or α-MSH, leading to a lack of MC4R functioning and obesity." (PMID 37937009, 2023).
Obesity (continued). "Total ghrelin levels are suppressed in non-PWS children and adults with exogenous obesity or with obesity caused by mutations in leptin or the melanocortin-4 receptor." (PMID 37175718, 2023). "Mc4r+/– and Mc4r–/– mice recapitulate the obesity phenotypes observed in humans." (PMID 36692018, 2023). "In 2020, the Food and Drug Administration (FDA) approved the first treatment involving the MC4R agonist setmelanotide for chronic weight management in adult and pediatric patients at least 6 years of age with obesity due to three rare genetic conditions: POMC, LEPR, or PCSK1 deficiency." (PMID 37571382, 2023). "When the effects of MC4R variants were considered, BMI in the individuals with MC4R variants between lean (n = 11) and individuals with obesity (n = 22) was not significant (p = 0.105)." (PMID 37025415, 2023). "Nearly 90% of the studies reported that the rs17782313 polymorphism has a significant impact on obesity risk, while only 50% of the studies on average reported that MC4R exonic polymorphisms are significantly related to obesity risk (data not shown)." (PMID 37621650, 2023). "Although the rs17782313 polymorphism is just localized near, but not within the MC4R gene, its impact on obesity risk seems to be greater than those polymorphic loci located in the MC4R gene." (PMID 37621650, 2023). "In addition to obesity most of the MC4R patients were noticed to have a tall stature (>95th height percentile)." (PMID 37329217, 2023). "The well-studied monogenic obesity genes BNDF, MC4R, and POMC were only identified by human GWAS, but such genes are likely important BMI factors in both species; for example, knockout mutations in Mc4r produce obesity phenotypes in rats." (PMID 37527041, 2023). "(n = 1,836) showed no significant gene-smoking or gene-alcohol interaction on obesity risk for MC4R genotypes." (PMID 37664850, 2023). "The highest prevalence of monogenic obesity was seen in a highly consanguineous population of Pakistan in a study of obese children that investigated only 3 monogenic obesity genes (LEP, LEPR, and MC4R) and found around 30% of the cases carried pathogenic variants." (PMID 37329217, 2023). "GLP-1R, 5-HT2CR and MC4R agonists have been developed for human obesity treatment." (PMID 36592795, 2023). "Genotype frequencies of MC4R rs17782313 SNP were 57.83% for the reference homozygote TT, 35.49% for the heterozygote TC, and 6.68% for the altered homozygote CC among individuals with obesity." (PMID 38002939, 2023). "Collectively, these data indicated that, in Mc4r-KO mice — a model of hyperphagic obesity without leptin deficiency in which hepatic DNL is increased to a lesser extent than in ob/ob mice — hepatic FASN deficiency ameliorated both NAFLD and diabetes." (PMID 37681411, 2023). "To date, MC4R genetic variation is the most common (2–8% of common obesity) cause of early-onset and the most severe monogenic non-syndromic obesity known, influencing eating behavior and hyperphagia." (PMID 38002939, 2023). "Obesity trials conducted with different MC4R agonists have, for example, reported cardiovascular disorders, gastrointestinal disorders (i.e., nausea and vomiting), erectile function disorders (penile erection) or skin hyperpigmentation with different administrations (i.e., oral and subcutaneous)." (PMID 37508552, 2023). "Most melanocortin trials targeted MC4R and were obesity-focused." (PMID 37508552, 2023). "In the last two decades, genome-wide association studies (GWAS) for obesity phenotype have shown a correlation between polymorphism in FTO and BMI, identifying two other polymorphisms associated with the phenotype that map in the proximity of the MC4R gene." (PMID 37375898, 2023). "Nevertheless, effects of some SNPs appear to be more pronounced in children and diminish later in life as has been shown for the associations of variants in TMEM18, GNDPA2, MC4R, NEGR1, BDNF and KTCD15 with early-onset obesity, and particularly for INSIG2 variants." (PMID 37819541, 2023).
Obesity (continued). "Furthermore, the MC4R rs17782313 has been studied with other obesity-related co-morbidities such as type 2 diabetes and cardiovascular diseases." (PMID 38002939, 2023). "Indeed, synthetic MC4R agonists are among the most studied pharmacological agents for obesity therapy." (PMID 37508552, 2023). "An increase in sympathetic nervous system effects is a major potential side effect for MC4R agonists that might outweigh the benefits of treating obesity." (PMID 37937009, 2023). "Early intervention with effective therapeutics that treat hyperphagia in rare MC4R pathway diseases that lead to obesity may alleviate the symptoms that contribute to lower health-related quality of life and diminished school performance." (PMID 37415189, 2023). "Moreover, antagonizing Gαs signaling specifically at the primary cilium of MC4R-expressing PVN neurons also leads to obesity, suggesting that not only does MC4R localize to cilia, but it functions in cilia to mediate energy homeostasis." (PMID 36692018, 2023). "Another important takeaway from GWAS is the fact that numerous common polymorphisms associated with polygenic obesity in ethnically diverse population have been found in genes like PCSK1, MC4R [43••] and POMC, known to carry rare loss of function variants leading to non-syndromic monogenic obesity." (PMID 37819541, 2023). "The most frequent causes of monogenic obesity are mutations in the genes leptin (LEP), leptin receptor (LEPR), melanocortin 4 receptor (MC4R), proopiomelanocortin (POMC), proprotein convertase subtilisin/kexin type 1 (PCSK1), and neurotrophic receptor tyrosine kinase 2 (NTRK2)." (PMID 37375898, 2023). "In addition, the result of a previous study showed that the probability of metabolically healthy obesity was higher in patients with the T/C genotype of MC4R rs1778231321." (PMID 37500675, 2023). "In this study, we also investigated the influence of two representative obesity-associated genes (FTO and MC4R) on body composition, metabolic parameters, and nutrient intake, as well as changes in these factors after intervention within the MeDiet group and control group." (PMID 35845810, 2022). "Therefore, MC4R has become a validated drug target for obesity therapy and several MC4R agonists achieved fabulous outcomes in phase III clinical trials, such as LY2112688 and setmelanotide." (PMID 35741395, 2022). "MC4R was heavily targeted by the pharmaceutical industry due to its role in obesity." (PMID 36291616, 2022). "On the contrary, MC4R knockout mice demonstrate hyperphagia and develop severe obesity and T2DM." (PMID 35328759, 2022). "Another study in eight adult Pima Indians with heterozygous pathogenic MC4R variants showed on average -140 kcal/day lower REE compared to non-genetic obesity controls." (PMID 35898454, 2022). "Other loci which have been implicated in severe childhood monogenic obesity include genes of the proopiomelanocortin (POMC), the melanocortin receptor 4 (MC4R), the protein convertase 1/3 (PC 1/3), the single-minded homolog 1 (SIM1), and the brain-derived neurotrophic factor (BDNF)." (PMID 36452324, 2022). "However, most MC4R agonist drug candidates developed as potential therapeutics for treating obesity failed in the clinic despite preclinical efficacy, due to lack of efficacy and side effects." (PMID 36291616, 2022). "Once patient A has reached a stable clinical condition, after stem cell transplantation, treatment with the MC4R agonist setmelanotide may be considered as a therapeutic option to treat her hyperphagia and obesity." (PMID 35737586, 2022). "When the investigators knocked out the MC4R gene in mice, the mice demonstrated severe obesity." (PMID 35114968, 2022). "Genetic disruption of MC4R dispaly hyperphagia, hyperinsulinemia, and obesity." (PMID 35163521, 2022). "The higher constitutive activity of hMC4R is pivotal in regulating energy homeostasis and increased basal activity of MC4R might protect against obesity." (PMID 35204745, 2022).
Obesity (continued). "Understanding the mechanism by which MC4R agonists mediate their effects on sexual behavior is important, not only for the ongoing development of melanocortin-based therapies for psychosexual disorders but also for obesity medicine, where related MC4R agonists are rapidly being developed." (PMID 36189794, 2022). "MC3R and MC4R knockout mice develop obesity while control mice do not, but the obesity phenotype differs between the two knockout variants." (PMID 35328759, 2022). "Thus, we feel that care should be taken in the attribution of the obesity phenotypes induced by exogenous GPR88* expression in MC4R‐expressing neurons of the PVN to the inhibition of ciliary AC3 expression." (PMID 34783461, 2022). "Selected ORGs expression, namely the fat mass and obesity-associated (FTO), melanocortin-4 receptor (MC4R), glucosamine-6-phosphate deaminase 2 (GNPDA2), and transmembrane protein 18 (TMEM18) were evaluated in testes and spermatozoa by a quantitative polymerase chain reaction (qPCR)." (PMID 36289871, 2022). "The relationship between MC4R and obesity was significant only in postmenopausal women." (PMID 36233190, 2022). "Numerous studies have elucidated the role of the MC4R pathway and, to a lesser extent, the MC3R in the regulation of food intake and energy expenditure, with impaired signaling through these receptors being associated with obesity." (PMID 35737586, 2022). "Overall, Mc4r−/− mice under HFD for 20 weeks develop both obesity and NASH with moderate fibrosis." (PMID 36555433, 2022). "The effect of the MC4R gene on obesity was modified by the living environment." (PMID 35495128, 2022). "MRAP2-deficient mice develop severe obesity, which is presumably resulting from a significant decrease in MC4R sensitivity to α-MSH in the absence of MRAP2 protein." (PMID 35741395, 2022). "In this respect, MC4R has been a prime pharmaceutical target for obesity." (PMID 35818295, 2022). "Early-onset severe obesity with hyperphagia is a hallmark phenotype associated with defective POMC, following the lack of POMC processing to α-MSH, d-α-MSH, and β-MSH, the most important ligands of the MC4R in the hypothalamus." (PMID 35737586, 2022). "Constitutive activity defect of MC4R leads to obesity suggesting the basal component activity of MC4R acts as a tonic satiety signal, which may be necessary to maintain long-term energy homeostasis in human." (PMID 35250878, 2022). "Furthermore, potential interactions between above factors and MC4R rs17782313 for obesity have been also tested." (PMID 36123585, 2022). "Therefore, targeting the MC4R for anti-obesity treatment appeared obvious, but was rather unsuccessful for a long time." (PMID 36009013, 2022). "Expression of ASIP is normally limited to the skin, where it affects pigmentation, while ubiquitous expression of ASIP causes other physiological functions, such as its expression in central nervous system resulting in obesity by inhibiting the function of MC4R." (PMID 36291616, 2022). "MC4R is expressed in the hypothalamic nuclei and regulates food intake and body weight; thus, Mc4r-KO mice cannot control their appetite and exhibit symptoms such as obesity, insulin resistance, and liver steatosis similar to those of NASH in humans." (PMID 35101153, 2022). "The results of this study suggest that polymorphisms of the MC4R, PPARGC1A, MSRA, and TFAP2B genes may be associated with obesity-related traits in a sample of Portuguese children." (PMID 36499740, 2022). "POMC deficiency results in the absence of its cleavage products, and inactivation of MC4R, thus causing hyperphagia, severe obesity, and red hair." (PMID 36452324, 2022). "Both MC3R and MC4R were critical for central control of appetite and energy homeostasis, which could be targeted as drug candidates for obesity or anorexia." (PMID 35250878, 2022). "Both MC4R-deficient mice and MOR-deficient mice show improved glucose tolerance despite obesity." (PMID 36210455, 2022).